TRPA1 (transient receptor potential cation channel subfamily A member 1)
Diseases named in the same sentence as TRPA1 in open-access papers (continued):
Sharing a sentence is not in itself a finding about the gene and the disease.
colorectal cancer (3 papers, 2024 to 2025). A primary or metastatic malignant neoplasm that affects the colon or rectum. "High expression of TRPA1 has been observed in several types of cancer, including breast, lung, pancreatic, and colorectal cancer." (PMID 38430394, 2024). "Elevated expression levels of PAX6, BCL11B, MCOLN2, CUX1 and EMX1 reported in colorectal cancer positively correlate with TRPA1 in other malignancies, with a possible implication in tumorigenesis." (PMID 39770499, 2024).
cutaneous melanoma (3 papers, 2021 to 2024). A primary melanoma arising from atypical melanocytes in the skin. "The authors showed that the number of intratumoral and peritumoral M2 macrophages and the amount of 4-HNE progressively increased with tumor severity in cutaneous melanoma samples, while TRPA1 protein expression remained unchanged." (PMID 37174661, 2023). "Here, we localized MΦs, the final end-product of oxidative stress, 4-hydroxynonenal (4-HNE), and TRPA1 in tissue samples of human common dermal melanocytic nevi, dysplastic nevi, and thin (pT1) and thick (pT4) cutaneous melanomas." (PMID 34831352, 2021). "Therefore, TRPA1 activation could amplify oxidative stress in cutaneous melanoma to amplify tumor progression." (PMID 37174661, 2023).
dementia (3 papers, 2019 to 2023). Loss of intellectual abilities interfering with an individual's social and occupational functions. "TRPA1-mediated LIF production is a promising target for vascular cognitive impairment, linked to various types of dementia." (PMID 37478173, 2023). "The aim of our study was to investigate the potential role of TRPA1 in a mouse model of senile dementia." (PMID 31327098, 2019).
emphysema (3 papers, 2020 to 2025). "In the present study, histopathological evaluation demonstrated duration-dependent chronic inflammation with edema formation, peribronchial, perivascular and parenchymal immune cell infiltration and emphysema in response to CSE in the lung of Trpa1+/+ mice, in agreement with our previous data." (PMID 40148437, 2025).
fibromyalgia (3 papers, 2023 to 2026). A chronic disorder of unknown etiology characterized by pain, stiffness, and tenderness in the muscles of neck, shoulders, back, hips, arms, and legs. "Studies have linked TRPA1 to heightened sensitivity to mechanical and cold pain in fibromyalgia patients." (PMID 41906627, 2026). "Future translational studies will be essential to validate whether pharmacological modulation of the Schwann cell TRPA1/NOX1 pathway could provide clinical benefit in fibromyalgia." (PMID 41906627, 2026).
glaucoma (3 papers, 2020 to 2024). Increased pressure in the eyeball due to obstruction of the outflow of aqueous humor. "Thus, it is possible that inhibition of a TRPA1-dependent pathway could also attenuate glaucoma-related retinal damage." (PMID 32801314, 2020).
infarction (3 papers, 2021 to 2024). A localised pathological necrosis of tissue resulting from obstruction of the blood supply usually by a thrombus, an embolus, or vascular torsion. "TRPA1 signaling deficiency in the endothelium of the cerebral arteries intensified cerebral infarctions in the mice model of permanent middle cerebral artery occlusion (MCAO)." (PMID 38333756, 2024). "Their results suggest that TRPA1 could activate fibroblasts and might contribute to myocardial repair after infarction." (PMID 36103570, 2022). "In cell culture studies, pharmacological activation of TRPA1 channels with ASP 7663 or optovin has been reported to reduce cell death and infarction size in an in vivo rat IR model." (PMID 34174803, 2021).
Insulin resistance (3 papers, 2022 to 2025). Increased resistance towards insulin, that is, diminished effectiveness of insulin in reducing blood glucose levels. "The effect of cinnamaldehyde on insulin resistance is mediated by TRPA1, with downstream signaling involving the activation of PI3-K, MAPK, PKC, as well as extracellular and stored calcium." (PMID 39861427, 2025). "The effects of CIN on insulin resistance were mediated by TRPA1, with downstream signaling involving the activation of PI3-K, MAPK, PKC, as well as extracellular calcium and calcium release from intracellular stores." (PMID 39861427, 2025). "In addition, AITC and cinnamaldehyde interact directly with TRPA1 to improve insulin secretion and weaken insulin resistance, thereby showing anti-diabetic effects." (PMID 39273183, 2024). "TRPA1, a channel that has been extensively studied for its association with glucagon-like peptide-1 (GLP-1) and insulin secretion, is suitable as an effective therapeutic target for dietary insulin resistance and associated diseases." (PMID 39273183, 2024). "In this context, the complex role of TRPA1 in insulin resistance suggests that the regulation of TRPA1 activation could be a novel therapeutic strategy, although additional studies are needed to properly elucidate this pathway in MS." (PMID 35455971, 2022). "Hypothesizing that the plasma membrane protein, transient receptor potential ankyrin-1, is a pivotal target in insulin resistance, we investigated the mechanism of action of cinnamaldehyde (CIN), an electrophilic TRPA1 agonist, in skeletal muscle, a primary insulin target." (PMID 39861427, 2025).
intracerebral hemorrhage (3 papers, 2019 to 2025). A cerebrovascular disorder characterized by bleeding into one or both cerebral hemispheres including the basal ganglia and the cerebral cortex. "Intracerebral hemorrhages were smaller in Trpa1-ecKO mice compared to controls, suggesting that TRPA1 channel activity-associated vasodilation and subsequent increase in cerebral blood flow may lead to hematoma expansion during intracerebral hemorrhage events." (PMID 36793787, 2023). "We propose ROS-activated endothelial cell TRPA1 channels enhance cerebral blood flow, resulting in more profound blood extravasation during intracerebral hemorrhage events." (PMID 36793787, 2023). "Similarly, in models of intracerebral hemorrhage, reactive astrocyte proliferation and elevated Ca2+ activity are attenuated by Trpa1 knockout, highlighting TRPA1 as a key regulator of injury-related astrocytic Ca2+ influx." (PMID 41383745, 2025).
lung disease (3 papers, 2020 to 2024). "In pulmonary diseases, TRPA1 activation leads to increased release of IL-8 and matrix metalloproteinase 9 gene expression in lung fibroblasts, suggesting a pro-fibrotic role." (PMID 38635081, 2024). "We propose that the paradigm of Th1 and Th2 inflammation is a major determinant of TRPA1 expression and function, which should be considered when targeting TRPA1 for pharmacotherapy in inflammatory (lung) disease." (PMID 37386145, 2023). "We propose that the paradigm of Th1 and Th2-type inflammation is a major determinant of TRPA1 expression and function, and this should be considered when targeting TRPA1 for pharmacotherapy in (lung) disease." (PMID 37386145, 2023). "TRPA1 also modulated the expression of genes relevant to innate immunity and lung disease." (PMID 37386145, 2023). "In light of the reports indicating that TRPA1 channels may be a potential molecular target for lung diseases, and since caffeine can suppress TRPA1 activity, we examined whether 832, 869, and 145 affect the function of this channel." (PMID 32503342, 2020). "Therefore, it is believed that TRPA1 antagonists may serve as a promising therapeutic alternative for lung diseases." (PMID 32503342, 2020).
mood disorder (3 papers, 2023 to 2026). A cognitive disorder a disturbance in which the person's mood is hypothesized to be the main underlying feature. "This age-related dynamics of Trpa1 and UCN1 expression of 3xTg-AD mice suggests that altered UCN1 signaling may contribute to AD-associated mood disorders and memory decline." (PMID 41876672, 2026).
occupational asthma (3 papers, 2016 to 2021). Asthma attacks caused, triggered, or exacerbated by OCCUPATIONAL EXPOSURE. "Toluene diisocyanate is a potent TRPA1 activator and exposure to this chemical is the leading cause of occupational asthma." (PMID 27827953, 2016). "The novel TRPA1 antagonist HC030031 was shown to improve epithelial barrier integrity in a toluene diisocyanate-induced model of occupational asthma." (PMID 33557843, 2021). "Interestingly, these symptoms were absent in TRPA1 KO mice suggesting an important role of TRPA1 in allergic or occupational asthma and rhinitis." (PMID 27827953, 2016).
osteosarcoma (3 papers, 2024 to 2025). A usually aggressive malignant bone-forming mesenchymal neoplasm, predominantly affecting adolescents and young adults. "A higher expression of TRPA1 was correlated with decreased migration of tumour cells and improved survival in osteosarcoma." (PMID 39940997, 2025). "We provide here the first data on the functional expression of the TRPA1 and TRPV1 ion channels in osteosarcoma, suggesting novel diagnostic and/or therapeutic perspectives." (PMID 38612571, 2024). "In addition, lipoyl-derived TRPA1 antagonists have been found to effectively inhibit the migration of osteosarcoma cells and suppress the expression of pro-inflammatory cytokines." (PMID 38612571, 2024). "Furthermore, a study employing lipoyl-based TRPA1 antagonists demonstrated their ability to decrease the migration of osteosarcoma cells and reduce the expression of pro-inflammatory cytokines." (PMID 38612571, 2024). "Both TRPA1/Trpa1 and TRPV1/Trpv1 were expressed similarly in human and mouse osteosarcoma tissues, while Trpa1 transcripts were more abundantly present in K7M2 cells." (PMID 38612571, 2024). "In our study we aim to characterize the expression and functionality of the TRPA1 and TRPV1 channels in human and mouse osteosarcoma tissues and in a mouse cell line." (PMID 38612571, 2024).
periodontitis (3 papers, 2022 to 2023). An acute or chronic inflammatory process that affects the tissues that surround and support the teeth. "This study is aimed at exploring the role and the novel therapeutic function of TRPA1 in periodontitis." (PMID 35720191, 2022). "In vivo, less periodontium destruction, oxidative stress, and apoptosis in periodontium were observed after TRPA1 inhibitor administration; thus, TRPA1 was considered an attractive therapeutic target in periodontitis." (PMID 35720191, 2022). "In conclusion, TRPA1 was highly related to periodontitis, and the oxidative, apoptotic levels and TRPA1 expression were obviously higher in P-PDLC/Ts from clinical periodontitis patients, inflammatory PDLCs in vitro, and periodontitis mice in vivo." (PMID 35720191, 2022). "TRPA1 was highly related to periodontitis, and TRPA1 inhibitor significantly reduced oxidative and apoptotic levels in inflammatory PDLCs via inhibiting ER stress by downregulating PERK/eIF2α/ATF-4/CHOP pathways." (PMID 35720191, 2022). "Periodontal ligament cells or tissues derived from healthy and periodontitis (PDLCs/Ts and P-PDLCs/Ts) were used to analyze the oxidative and apoptotic levels and TRPA1 expression." (PMID 35720191, 2022). "The oxidative, apoptotic levels and TRPA1 expression were higher in P-PDLC/Ts from periodontitis patients and in P.g.LPS-induced inflammatory PDLCs." (PMID 35720191, 2022). "TRPA1 inhibitor inhibits endoplasmic reticulum stress by downregulating the PERK/eIF2α/ATF-4/CHOP pathway and reducing oxidative stress and apoptosis in periodontitis mice, thereby improving periodontitis." (PMID 36875034, 2023). "This study proved a significant activation and increase of TRPA1 in P-PDLC/Ts from periodontitis and in LPS-induced inflammatory PDLCs but not in the HC pretreatment group." (PMID 35720191, 2022). "Therefore, it is possible that periodontitis-induced TRPV1/TRPA1 signaling triggers SP secretion from nociceptors in ligature-induced periodontists." (PMID 37122730, 2023).
peripheral nerve injury (3 papers, 2017 to 2024). Injury to a peripheral nerve. "To explore the potential mechanisms which baicalin involved in the prevention of neuropathic pain, we examined Trpv1 and Trpa1 mRNA expression in DRG of rats with peripheral nerve injury using quantitative RT‐PCR method." (PMID 32613759, 2020). "In addition, multiple studies have shown that TRPA1 is a mechanosensitive cation channel, and inhibition of the expression of the TRPA1 can effectively alleviate mechanical nociception after peripheral nerve injury." (PMID 39104725, 2024). "Previous studies has revealed that Annexin A2 regulates TRPA1-dependent nociception and may have an important role in neuropathic pain after peripheral nerve injury." (PMID 28928629, 2017). "After peripheral nerve injury, the expression of TRPV1 and TRPA1 increases, and Ca2+ flow in and combine with CaM to act on nNOS to produce NO." (PMID 39104725, 2024).
Psoriasiform dermatitis (3 papers, 2019 to 2022). A skin abnormality characterized by redness and irritation, with thick, red skin that displays flaky, silver-white patches (scales). "The function of TRPA1, however, in psoriasiform dermatitis (PsD) is uncertain." (PMID 31111624, 2019).
renal fibrosis (3 papers, 2022 to 2024). A final common manifestation of a wide variety of chronic kidney diseases characterized by glomerulosclerosis and tubulointerstitial fibrosis. "Collectively, these data indicate that TRPA1 is a downstream mediator of the inhibitory effects of PRDM16 on renal fibrosis." (PMID 38072665, 2024). "To investigate the role of TRPA1 in renal fibrosis, we knocked down TRPA1 in BUMPT cells and then treated the cells with HG for 48 h." (PMID 38072665, 2024). "In our previous study, NF-κB was found to mediate the upregulation of PRDM16, thereby inhibiting renal fibrosis through the transient receptor potential ankyrin 1 (TRPA1)/mitogen-activated protein kinase (MAPK)/transforming growth factor-β1 (TGF-β1) axis." (PMID 39549609, 2024). "Mechanistically, we have further collected evidence that TRPA1 may suppress renal fibrosis by blocking MAPK (P38 and ERK1/2) activation and consequent TGF‐β1 expression." (PMID 38072665, 2024). "TRPA1 can be activated by toxic or inflammatory mediators (such as ROS), and activation of TRPA1 may aggravate the inflammatory response and lead to renal fibrosis." (PMID 36278189, 2022). "We further determined whether TRPA1 acts downstream of PRDM16 for suppressing renal fibrosis." (PMID 38072665, 2024).
respiratory depression (3 papers, 2015 to 2020). A decrease in ventilation secondary to impaired signals from the central nervous system. "TRPA1-deficient (TRPA1−/−) mice were protected from OCl−-induced respiratory depression." (PMID 30087301, 2018). "Both genetic and pharmacological blockade of TRPA1 indicate its probable contribution to mild hypoxia-induced respiratory excitation and, to a lesser extent, hyperoxia-induced respiratory depression." (PMID 33192579, 2020). "TRPA1 activation leads to pain and reflex (sneezing, cough, and respiratory depression and avoidance), therefore serves as a protection to limit or eliminate irritant exposure." (PMID 25640188, 2015). "Activation of TRPA1 by acrolein, ozone, and chlorine leads to pain, mucus secretion, sneezing, cough, and respiratory depression." (PMID 25640188, 2015).
retinoblastoma (3 papers, 2015 to 2024). A malignant tumor that originates in the nuclear layer of the retina. "On the other hand, TRPA1 is completely suppressed in a retinoblastoma cell line, which is resistant to the cytostatic agent etoposide." (PMID 26818117, 2015). "Another study revealed TRPV1, TRPM8 and TRPA1 gene expression in retinoblastoma cells." (PMID 26605361, 2015). "Interestingly, the expression of TRPA1 was completely suppressed in a retinoblastoma cell line, which is resistant to the cytostatic agent etoposide." (PMID 26605361, 2015). "Other TRPs like TRPV1, TRPM8 and TRPA1 are expressed in retinal tumor cells (retinoblastoma)." (PMID 26818117, 2015). "TRPV1, TRPM8 and TRPA1 are expressed in retinal tumour cells (retinoblastoma)." (PMID 26605361, 2015). "In the case of cattle, genes like TRPA1, RB1 and SCNN1B are predicted to be involved in respiratory diseases, retinoblastoma and renal diseases, respectively." (PMID 38674383, 2024).
trigeminal neuralgia (3 papers, 2016 to 2025). Trigeminal neuralgia is a nerve disorder that causes a stabbing or electric-shock-like pain in parts of the face. "Consistently, we previously reported upregulated levels of TRPA1 mRNA in the areas containing the TNC after induction of experimental trigeminal neuralgia in rats." (PMID 40363691, 2025). "Antagonism of transient receptor potential ankyrin type-1 (TRPA1) channels counteracts the experimentally induced trigeminal neuralgia (TN) pain." (PMID 40363691, 2025). "CSF from control patients does not activate any sampled WT neurons, further suggesting that unique components of CSF from patients with trigeminal neuralgia can activate endogenous TRPA1." (PMID 35921423, 2022). "We report that cerebrospinal fluid from patients with trigeminal neuralgia accumulates reactive oxygen species, several of which directly activate the pain-transducing channel TRPA1." (PMID 35921423, 2022). "A mouse model of trigeminal neuralgia similarly accumulates ROS, several of which directly activate TRPA1." (PMID 35921423, 2022). "Of the 13 trigeminal neuralgia cases we screened, CSF from all but 4 activates TRPA1-expressing HEK cells." (PMID 35921423, 2022). "To confirm that CSF from patients with trigeminal neuralgia can also activate TRPA1 in its native, neuronal environment, we applied CSF from patients with trigeminal neuralgia and controls to wild-type (WT) and TRPA1-null (TRPA1−/−) trigeminal neuronal cultures." (PMID 35921423, 2022). "The potent antinocifensive effects of blocking or eliminating TRPA1 suggest that its inhibition might be a therapeutic strategy in managing trigeminal neuralgia." (PMID 35921423, 2022). "As TRPA1 seems central to pain in the constrictive mouse model of trigeminal neuralgia, we wondered whether activating the NRF2 antioxidant network might lessen allodynia by countering redox stress." (PMID 35921423, 2022). "As endogenous TRPA1 responds to CSF from patients, we tested whether pharmacologically inhibiting or genetically eliminating TRPA1 would blunt pain in the constrictive mouse model of trigeminal neuralgia." (PMID 35921423, 2022). "Since TRPA1 senses H2O2 and 4-HNE in isolation, we wondered whether it may respond similarly to CSF from patients with trigeminal neuralgia." (PMID 35921423, 2022).
uveal melanoma (3 papers, 2015 to 2021). A melanoma derived from melanocytes of the uveal tract. "A similar association pertains to TRPA1 because its expression is lower in human uveal melanoma cells than in healthy uvea." (PMID 26818117, 2015). "Functional TRPV1, TRPM8, and TRPA1 were also expressed in malignant human uveal melanoma tissues and cell lines." (PMID 34831352, 2021). "In contrast, in human uveal melanoma cells, the gene expression of TRPM8 is at lower levels whereas the TRPA1 expression is at high levels in healthy uvea." (PMID 26818117, 2015). "Therefore, it is suggested that identification of functional TRPV1, TRPM8, TRPA1 and CB1 expression in uveal melanoma may provide novel drug targets for treatment of this aggressive neoplastic disease." (PMID 26818117, 2015).